HIF1A (hypoxia inducible factor 1 subunit alpha)
Diseases named in the same sentence as HIF1A in open-access papers (continued):
Sharing a sentence is not in itself a finding about the gene and the disease.
cancer (continued). "HIF‐1β predominately binds HIF‐1α or aryl hydrocarbon receptor (AhR) to form heterodimer complexes that regulate transcription of target genes involved in various physiological and pathological processes, including cancer." (PMID 29926531, 2018). "The high level of HIF-1α aids the cancer cells in their resistance against treatment and death." (PMID 30002330, 2018). "In addition to hypoxia, aberrant oncogenic signaling in cancer cells has been shown to facilitate the normoxic stabilization of HIF-1α to rewire the metabolism by inducing the expression of PKM2." (PMID 29468140, 2018). "HIF-1α has previously been reported to modulate CKα expression and PC levels in cancer." (PMID 29619216, 2018). "Therefore, we believe that disruption of the HIF-1α/SEPT9_i1 complex is beneficial for cancer therapy, and that the BiFC system is vitally important for evaluating novel compounds capable of disrupting the protein-protein interaction." (PMID 28380438, 2017). "In cancer patients, high plasma hLDH5 levels can serve as a malignant cell biomarker, since it is associated with induction by HIF-1α and MYC, rather than nonspecific cellular damage." (PMID 29257069, 2017). "Although HIF-1α dysregulation has been found in a wide variety of cancers, several studies indicate that HIF-2α upregulation is more commonly associated with an aggressive phenotype and poor prognosis in neural crest cell tumors, including PHEO/PGL and neuroblastoma." (PMID 28423608, 2017). "HIF1A was commonly found to locate in the nucleus of most cancers and absented in normal controls." (PMID 27902480, 2017). "Interplay of MCL-1 and HIF-1α have shown to be variable in different tissues and cancers." (PMID 28404924, 2017). "However, many other studies have indicated that knockdown of HIF-1α sensitizes various types of human cancer cell types to apoptosis." (PMID 28476028, 2017). "Cell cycle progression, where the CDKN1 proteins act as natural inhibitors may be functionally linked via pVHL to the HIF-1α and HIF-2α-dependent pathways, i.e. hypoxia/angiogenesis response, which is particularly relevant in cancer development." (PMID 28425505, 2017). "Interestingly, transcription factor HIF1α (Hypoxia inducible factor 1 alpha subunit) has been shown to promote a switch from collective to highly contractile cancer amoeboid mode of migration under hypoxic stimuli." (PMID 28715714, 2017). "We anticipate that complex 1 could be utilized as a promising scaffold for the further development of more potent HIF-1α inhibitors for anti-cancer treatment." (PMID 28225008, 2017). "Furthermore, it is clear that HIF1A expresses in both cytoplasm and nuclei of a cell and exerts different functions in cancer progression." (PMID 27902480, 2017). "To assess the contribution of HIF-1α to the GATA3-mediated cancer cell invasiveness, we knocked down endogenous HIF-1α or expressed N-HIF-1α in Mock or GATA3 stable transfectants and then carried out transwell migration and Matrigel invasion assays under hypoxia." (PMID 28263977, 2017). "IDF-11774 inhibited HIF-1α accumulation and the growth of various cancer cells." (PMID 28569777, 2017). "Hypoxic (≤3% oxygen) and anoxic (≤0.3% oxygen) cancer cells display increased proliferation, increased angiogenesis and metastatic drive, and therapy resistance, due in part to the induction and activation of the hypoxia-inducible transcription factor HIF1-α." (PMID 29137421, 2017).
cancer (continued). "HIF‐1α has been reported to promote cancer progression through multiple mechanisms." (PMID 28028936, 2017). "Our results show that Parkin ubiquitinates and degrades HIF-1α, suggesting that Parkin may play a critical role in inhibiting cancer metastasis through its downregulation of HIF-1α." (PMID 29180628, 2017). "The correlation between MVD and HIF1A expression has been found in many cancers, including GC." (PMID 27902480, 2017). "Since both AP-1 and HIF-1α are known to be substrates of APE1 and the redox activity of APE1 is reported to be associated with angiogenesis in cancer, we asked whether APE1 is crucial for KSHV-induced angiogenesis in PDLSCs." (PMID 28380040, 2017). "Although augmented HIF-1α signalling has been well associated with elevated glycolytic flux and FDG uptake in human cancers, it is evident that tissue-specific metabolic regulation may contribute to further heterogeneity in glucose metabolism." (PMID 28548087, 2017). "In the present study we found that inhibition of the mTORC2 component RICTOR impairs activation of signaling pathways (AKT, SGK1), reduces expression of hypoxia-induced HIF-1α and diminishes secretion of critical cancer-promoting factors involved in stromal recruitment such as VEGF-A and IL-8." (PMID 28445935, 2017). "Either western blotting or immunofluorescence for HIF1α showed that compared with 2D-grown cancer cells, 3D-grown cancer cells showed significantly higher expression of HIF1α, a molecular indicator of the hypoxic environment (for western blotting: 2D, 0.4190 ± 0.0205; 3D, 0.5287 ± 0.0297; P < 0.01)." (PMID 29200966, 2017). "Here, we report that GATA3 functions as an HIF-1α regulator to promote cancer cell invasiveness." (PMID 28263977, 2017). "This suggests that HIF-1α status might be a valid marker for predicting the sensitivity of cancers to chemotherapies." (PMID 28790395, 2017). "We found upregulation of ETS‐1 by CoCl2 treatment, which is reduced upon silencing of HIF‐1α, suggesting that there might be some existing regulation between ETS‐1 and HIF‐1α in cancer." (PMID 28236660, 2017). "HIF-1α regulates several target genes involved in many aspects of cancer progression, including angiogenesis, metastasis, anti-apoptosis and cell proliferation as well as imparts resistance to cancer treatment." (PMID 28165392, 2017). "A high amount of adipocytes enhances cancer progression due to the increased expression of HIF-1α." (PMID 28993797, 2017). "HIF-1α is a key regulator of cancer metabolism particularly in anaerobic condition." (PMID 28915611, 2017). "Collectively, AE-AS may be a potential anticancer agent by attenuating cancer angiogenesis via suppression of WSB-1/pVHL/HIF-1α/VEGF/VEGFR2 cascade." (PMID 28710377, 2017). "MVD in nucleic HIF1A+ were significant higher compared with cytoplasmic HIF1A+ in cancer tissues." (PMID 27902480, 2017). "Moreover, silencing the HIF-1α gene completely abrogated the UCHL1-mediated radioresistance of cancer cells." (PMID 28761052, 2017). "If HIF-1α expression is inhibited in cancer cells, aggressive behaviors decrease in these cells." (PMID 29152137, 2017). "We also investigated whether the HIF-1α-inhibiting effect of emodin and rhein, if any, attenuated cancer cachexia in the athymic mice that carried the cancer cells." (PMID 29152137, 2017). "The Na+/H+ exchanger NHE1 plays a major role in cancer development, is regulated by hypoxia and was recently proposed to play a role in HIF-1α-induced angiogenesis, yet its roles in endothelial cell signaling under hypoxia as compared to TME conditions have not been studied." (PMID 28806945, 2017). "Many malignant tumors are characterized by low oxygen conditions, which trigger the hypoxia-inducible factor 1α (HIF-1α)-mediated overexpression of a series of proteins that activate signaling pathways necessary for the survival of cancer cells under these conditions." (PMID 29236080, 2017).
cancer (continued). "Notably, this bioenergetic regulation contributes to retrograde signaling, as SDH inhibition by TRAP1 impacts on the nuclear transcriptional profile of cancer cells through succinate-mediated HIF1α stabilization, thus promoting cancer growth." (PMID 28405578, 2017). "Indeed, in low oxygen tension HIF-1α is quickly stabilized and affects most of the cancer hallmarks involved in the hypoxic response." (PMID 28214471, 2017). "In addition to these, other cancer stemness associated genes including EPCAM (1.6 folds), ALDH2 (1.3 folds), ALDH1A3 (0.9 folds) and HIF1A (0.7 folds) are all found up-regulated though to less extent." (PMID 28698547, 2017). "Pro is reported to increase HIF-1α expression in cancer cells." (PMID 28526934, 2017). "Indeed, our results show the radiosensitizing effect of OL is greatly reduced in cancer cells overexpressing HIF1α, suggesting the effect of OL is mediated via reducing HIF1α expression." (PMID 28057028, 2017). "Also, several studies in cancer cells showed that microtubule remodelling occurred under hypoxic conditions, and that HIF1A transcriptional activity mediated beta-tubulin expression." (PMID 28413565, 2017). "We thank the Cancer Metabolism Group (Nuffield Department of Medicine, Oxford University, Oxford, UK), in particular Dr Patrick Pollard, Dr Julia Adam and Dr Norma Masson for the use of hypoxia chambers, HIF1A antibody and their technical advice." (PMID 29137421, 2017). "This is reflected by the differential expression of HIF1α for 2D versus 3D cultured cancer cells." (PMID 29200966, 2017). "Our findings indicate that DDP-based chemotherapy combined with targeting the HIF-1α-regulated cancer metabolism pathway might be an ideal strategy to treat PCa." (PMID 28790395, 2017). "However, the detailed mechanisms by which OL reduces the levels of VEGFs and HIF-1α, and the crosstalk between cancer cells, M2-MΦs and adipocytes remain to be elucidated." (PMID 28410190, 2017). "The high activation level of STAT3 under hypoxia, an oncoprotein strongly implicated in chemoresistance in cancer cells, has led us to hypothesize that STAT3 sustained the chemoresistant phenotype despite the effective experimental abrogation of HIF-1α." (PMID 29036915, 2017). "In over 70% of human cancers and metastases, overexpression of HIF-1α has been verified." (PMID 28974006, 2017). "These kinases stablize HIF-1α by regulating of AKT in hypoxic cancer cells." (PMID 28165392, 2017). "Such a strategy may also affect the polarization of TAMs as well as the metabolic symbiosis between CAFs and cancer cells in a HIF1α-dependent manner." (PMID 28447025, 2017). "We tested our hypothesis that the sensitivity of PCa cells to DDP could be enhanced by reducing HIF-1α-regulated cancer metabolism." (PMID 28790395, 2017). "A recently study showed OL could reduce the protein expression of hypoxia-inducible factor 1 α (HIF1α), which is a major regulator of the radiation response in cancer cells." (PMID 28057028, 2017). "Since both HIF1α and β-catenin are fundamental factors in developmental as well as cancer biology, we believe that these in vitro findings can contribute to understanding the mechanisms of neural differentiation under both physiological and pathophysiological conditions." (PMID 29422917, 2017). "HIF-1α pathways seem to have a role in ccRCC and in other cancers, with context dependent roles." (PMID 28594929, 2017). "Several reports have identified links between cancer outcomes and the level of HIF-1α protein." (PMID 29312568, 2017). "Collectively these reports demonstrate that celastrol has potential to be used in the treatment of different types of cancer, mainly due to its capacity to inhibit transcription factors, such as NF-kB and HIF-1α, and mediators of protein homeostasis, like HSP90 chaperon." (PMID 28664158, 2017). "The α subunit of HIF-1 (HIF-1a) is a well-established mediator in the cancer response to hypoxia." (PMID 28449718, 2017).
cancer (continued). "Therefore, inhibiting HIF-1α induction and its-evoked angiogenesis is a promising target for attenuating cancer progression." (PMID 28710377, 2017). "Several studies have been conducted to investigate how to reduce the ability of cells adapting to hypoxic conditions, where HIF-1α has emerged to be an attractive target for new anti -cancer therapies to improve the current treatments of metastatic and resistant cancers." (PMID 28214471, 2017). "Given that Daam2 expression is inversely correlated with VHL, we next assessed whether Daam2 demonstrates congruent correlation with HIF1α and pAkt in the panel of human cancers." (PMID 29053101, 2017). "Decreased HIF-1α abundance in cancer cells with STK33 deletion and exposed to hypoxia was associated with significantly impaired transcriptional activation of the HIF-Responsive Element (HRE), a HIF-1α docking site present in promoters that contain the RCGTG sequence." (PMID 29100402, 2017). "The role of HIF-1α in cancer cells metabolism has been extensively demonstrated." (PMID 28933733, 2017). "Down-regulation of RBMS3 and up-regulation of HIF1A have been reported in some human cancers." (PMID 27902480, 2017). "β2-AR has been shown to regulate HIF-1α expression in cancer cells." (PMID 28855859, 2017). "As the association between lncRNA-LET and NF90 was shown to enhance the degradation of NF90, the hypoxia-induced downregulation of lncRNA-LET may thereby increase HIF-1A mRNA stability under hypoxic conditions and lead to hypoxia-induced cancer cell invasion." (PMID 28789687, 2017). "Activation of β2-adrenergic receptor (β2-AR) has been shown to upregulate HIF-1α in cancer cells." (PMID 28855859, 2017). "Furthermore, TXNIP expression is controlled by various transcriptional regulators like MondoA/MLX, MYC, and HIF1α, and is shown to be silenced in many cancers." (PMID 28124999, 2017). "High reactive oxygen species (ROS) levels produced by cancer cells were found to induce loss of Caveolin-1 in CAF leading to increased autophagy and ketone bodies generation along with enhanced glycolysis mediated through HIF-1α stabilization." (PMID 28848547, 2017). "Interestingly, these genes can be also targets of HIF-1α, highlighting the existence of an intricate crosstalk between inflammation and hypoxia in cancer cells (see Section 4)." (PMID 28536364, 2017). "Innovative and more effective cancer therapies can be developed by regulating HIF-1α expression, which is the key factor in hypoxia, and controlling the expression of IL-8 and other angiogenic stimulators, which restore the angiogenic processes, during inhibition of HIF-1α expression." (PMID 28053598, 2017). "Gal-3 is a pleiotropic carbohydrate-binding protein that can be located intracellular or secreted, whose expression is HIF1α-inducible, is a known angiogenic factor, and frequently has altered expression in cancer." (PMID 28695825, 2017). "This is the first study that provides in vivo evidences of coordinated activation of HIF-1α, CAIX, miR-210 and ISCU in carcinoma and association with poor prognosis, a finding with important implications for the development of metabolic-targeting therapies against hypoxia." (PMID 28099149, 2017). "Thus far, we showed that the AF2240 virulent strain of NDV caused degradation of HIF-1α and VHL in infected cancer cells." (PMID 27902314, 2016). "HIF-1α expression is also known to induce chemoresistance in cancer cells." (PMID 26967059, 2016). "Our insight into PHDs-mediated oxygen sensing machinery in cancer leads to a discovery of a regulator of HIF-1α stabilization that may open up an avenue for anti-cancer therapeutic strategies." (PMID 27966538, 2016). "However, how it regulates HIF-1α protein expression and cancer cell death under hypoxic conditions is unclear." (PMID 27263528, 2016).
cancer (continued). "Furthermore, the D-Fe3O4@PMn NPs enable targeted dual-contrast T1- and T2-weighted MR imaging of cancer cells expressing high levels of HIF-1α and cancer stem cell-related proteins under hypoxic condition." (PMID 27976736, 2016). "Interestingly, studies have shown that HIF-1α is a critical target of cardiac glycosides for cancer therapy." (PMID 26958938, 2016). "In conclusion, NPs with HIF-1α and Mn(II) are promising diagnostic agents for dual-mode T1 and T2 imaging by targeting cancer stem cells as they are non-toxic and biocompatible." (PMID 27976736, 2016). "This led us to hypothesise that BA mediated HIF-1α destabilisation may occur in other cancer cell lines." (PMID 27416726, 2016). "Thus, determining how HIF-1α downregulates Daxx expression is important in uncovering the mechanism of hypoxia-induced cancer metastasis." (PMID 28004751, 2016). "The expression profiles of low-grade cancer stroma reported here are consistent with Pavlides’ model of the RWE, which depend on ROS-induced and HIF1A-mediated transcription of genes encoding key glycolytic enzymes, transporters, and autophagic vesicle assembly factors." (PMID 27152194, 2016). "Furthermore, the activity and expression of SPHK-1 are significantly induced under hypoxia and by HIF-1α, and thus is a critical therapeutic target through pVHL-dependent proteasomal degradation for cancer treatment." (PMID 27581969, 2016). "Using DMOG, a pharmacological inhibitor of PHD, and siRNAs targeting individual PHD isoforms, we investigated whether PHD1 participates in the regulation of HIF-1α in hypoxic cancer cells." (PMID 27263528, 2016). "Cancer tissues can be exposed to hypoxia because of aberrant tumor vascularization, which induces the transcription of hypoxia inducible factors (HIFs) including HIF-1α and HIF-2α." (PMID 27589734, 2016). "In cancer cells, various oncogenic signalling pathways such as PI3K/AKT and Ras activate HIF-1 during normoxia by promoting the expression of HIF-1α, while inactivating mutations in the mitochondrial enzymes succinate dehydrogenase and fumarate hydratase stabilise HIF-1α7." (PMID 26948053, 2016). "Besides, a critical connection between redox and metabolic pathway in cancer cells is hypoxia-inducible factor 1α (HIF-1α) pathway." (PMID 27023612, 2016). "In the presence of Compound 7, HIF-1α protein levels were clearly decreased in HeLa, HepG2, and H1703 cells under hypoxic condition, indicating the similar effect of compound 7 in different types of cancer cells." (PMID 27611801, 2016). "We therefore hypothesize that polymorphism of HIF1A gene could lead to uncontrolled expression of HIF-1α protein in cancer." (PMID 26872370, 2016). "We further found that docetaxel-induced inhibition of HIF-1α increased hypoxic cancer cell death." (PMID 27263528, 2016). "Melatonin may restore the appropriate level of VEGF in the fetal heart by destabilizing the hypoxia‐induced HIF‐1α activity on the transcription of vegf, as reported in cancer cells." (PMID 26444711, 2016). "Several oncogenic pathways such as HIF-1α, c-Myc, PI-3K, and Ras play important roles in enhancing aerobic glycolysis and suppressing oxidative phosphorylation, thereby suggesting their involvement in the metabolic reprogramming of cancer cells." (PMID 26740011, 2016). "This is followed by the translocation of HIF1α and HIF1β dimers to the nucleus and subsequent HIF1α mediated transcription of a multiple genes that can promote angiogenesis, glucose metabolism, cell survival, proliferation, and metastasis in cancer." (PMID 27166196, 2016). "A previous study found that activating the AKT and ERK signaling pathways could enhance HIF-1a/VEGF expression in some malignant tumors." (PMID 27456341, 2016). "Third, we further confirmed that the Panc-1/HIF-1α+ subpopulation is enriched in cancer stem cells." (PMID 27976736, 2016).